GJB2 (gap junction protein beta 2)
Diseases named in the same sentence as GJB2 in open-access papers (continued):
Sharing a sentence is not in itself a finding about the gene and the disease.
hearing loss (continued). "Large deletions at the DFNB1 locus encompassing the GJB6 gene or neighboring regions have been reported in individuals presenting with hearing loss, either in homozygosis or in trans with a single recessive mutation in the GJB2 gene." (PMID 38626573, 2024). "Pathogenic DNA alterations in GJB2 are present in nearly half of non-syndromic hearing loss cases with autosomal recessive inheritance." (PMID 38626573, 2024). "To investigate the association between hereditary hearing loss and vestibular function, we compared vestibular function and symptoms among patients with GJB2, SLC26A4, and CDH23 variants." (PMID 38720048, 2024). "We identified a heterozygous c.250G>A (p.Val84Met) variant in GJB2 as the cause of the autosomal dominant syndromic hearing loss with the skin disorder in this Japanese family and delineated the pathological significance of the variant." (PMID 38550477, 2024). "GJB2 is the most common gene in non-syndromic hearing loss population, and the c.235delC mutation in GJB2 is the most frequently known mutation in some East Asian groups, with a carrier frequency of approximately 1%." (PMID 38456936, 2024). "This case study enriches our understanding of GJB2 mutations and underscores the critical role of genetic testing in diagnosing congenital sensorineural hearing loss." (PMID 39151510, 2024). "More than 300 different pathogenic DNA alterations have been reported in the GJB2 gene (Deafness Variation Database), the majority of which leading to prelingual hearing loss with autosomal recessive inheritance pattern." (PMID 38626573, 2024). "The audiological features of hearing loss (HL) in patients with autosomal recessive deafness type 1A (DFNB1A) caused by splice site variants of the GJB2 gene are less studied than those of patients with other variants of this gene." (PMID 39436953, 2024). "Several susceptibility genes for hearing loss are involved in potassium recycling, such as connexin genes (GJB2, GJB3), potassium channels or channel subunits (KCNQ1, KCNQ4) and Na+/2Cl-/K+ cotransporter (SLC12A2)." (PMID 39226169, 2024). "Consistent with this, SLC26A4 was identified as the most prevalent deafness-causing gene, accounting for approximately 20% of prelingual-onset NSHL cases, followed by GJB2, in a cohort of Korean patients with hearing loss." (PMID 39609929, 2024). "The Val84Met variant in GJB2 contributes to the autosomal dominant form of syndromic hearing loss with keratoderma." (PMID 38550477, 2024). "Normothermia TTM upregulated 13 genes associated with hearing loss, including Loxhd1, Tecta, Zmiz1, Espn, Gjb2, Sesn3, Bdp1, Hg, Pax3, Rnls, Syne4, P2rx2, and Pou3f4." (PMID 38298897, 2023). "Pathogenic missense variants in the GJB2 gene cause isolated hearing loss and hearing loss combined with skin diseases." (PMID 37106706, 2023). "Clarifying the pathological mechanism of GJB2-related hearing loss can help develop new prevention and treatment strategies." (PMID 37333892, 2023). "The GJB2-associated autosomal recessive non-syndromic hearing loss found for S2 is rather common (incidence about 1 in 2500 birth), differing from Townes–Brocks syndrome found for S3, and 8p inverted duplication and deletion syndrome found for S10." (PMID 36675424, 2023). "We recently showed that variants in GJB2 explained Hearing Impairment (HI) in 34.1% (n = 15/44) of multiplex families in Senegal." (PMID 36980833, 2023). "The reason for the increased burden in a few developed countries is in part related to inherited hearing loss, such as mutations in the GJB2 gene." (PMID 37824170, 2023). "Hearing loss caused by mutations in GJB2 accounts for approximately half of all autosomal recessive forms of hearing loss and is the most common form of hereditary hearing loss." (PMID 38069086, 2023).
hearing loss (continued). "In Israel, mutations include some responsible for hearing loss, such as GJB2 c.167delT and TMC1 p.Ser647Phe, while other deafness-causing mutations, such as GJB2 c.35delG, are common in all Jewish ethnicities and elsewhere." (PMID 37761399, 2023). "The GJB2 gene is the most common gene responsible for hearing loss (HL) worldwide, and missense variants are the most abundant type." (PMID 37106706, 2023). "One recent study showed the presence of GJB2 or GJB6 mutations in 38% of patients with non-syndromic hearing loss in Argentina." (PMID 37928735, 2023). "GJB2 variants are the most prevalent cause of hereditary hearing loss worldwide and are responsible for approximately 30% of deafness in Jewish families." (PMID 37761399, 2023). "GJB2 is one of the most important genes responsible for hearing loss, and missense variants are the most abundant variant type." (PMID 37106706, 2023). "We found that the contribution of the GJB2 gene variants to the etiology of hearing loss in Buryat patients is significantly lower (5.1%) than in Russian patients (28.9%)." (PMID 37239361, 2023). "Up to now, more than 100 mutations associated with human hearing loss have been identified in the region of GJB2 gene." (PMID 37333892, 2023). "The c.35delG (also known as c.30delG) and c.235delC alleles are the most common hearing loss-associated GJB2 alleles in the Caucasian and Asian populations, respectively." (PMID 37178259, 2023). "In the past, researchers generally believed that the pathological mechanisms underlying GJB2-related hearing loss comprised a K+ circulation defect and abnormal ATP-Ca2+ signals." (PMID 37333892, 2023). "The GJB2 gene is one of the first candidate genes in the study of genetic etiology in patients with hearing loss, which is explained by its well-studied frequency and spectrum of variants in many countries." (PMID 37239361, 2023). "Considering a carrier frequency of 3%, there are approximately 3.6 cases of hearing loss attributed to GJB2 mutations per 10,000 people." (PMID 38069086, 2023). "People with hearing loss due to GJB2 mutations also have variations from mild to profound hearing loss." (PMID 38069086, 2023). "Global research findings estimate the occurrence rate of autosomal recessive hearing loss caused by GJB2 mutations to be approximately 16.9%, with Europe exhibiting the highest prevalence (27.1%) and sub-Saharan Africa displaying the lowest prevalence (5.6%)." (PMID 37928735, 2023). "In this review, we summarize the pathological mechanisms of GJB2-related hearing loss, including aspects of K+ circulation, developmental disorders of the organ of Corti, nutrition delivery, oxidative stress and ATP-Ca2+ signals." (PMID 37333892, 2023). "Recent interest in the progression of hearing loss has emerged, revealing cases of moderate hearing loss with GJB2 mutations." (PMID 38069086, 2023). "The aim of our study is to evaluate the audiological features in patients with hearing loss caused by mutations in the GJB2, STRC, USH2A genes associated with mild, moderate, and moderate-to-severe SNHL." (PMID 36579563, 2022). "The severe-to-profound hearing loss observed in these two cases reflects the clinical phenotype of GJB2-associated hearing loss." (PMID 35022556, 2022). "Compared with the diagnostic strategy of analyzing only the GJB2 gene in the first step, our multiplex PCR detection strategy is more effective and economical for the Chinese hearing loss population." (PMID 36568381, 2022). "CNV analysis revealed the CNV of the STRC gene is the second most common etiology in cases of mild-to-moderate hearing loss after the GJB2 gene." (PMID 34599366, 2022). "GJB2:c.235del, which is associated with moderate to profound congenital hearing loss, is another frequent variant in the Chinese population." (PMID 35816303, 2022). "This is because there are hotspot genes and variants in the Chinese hearing loss population, such as GJB2 c.235del, SLC26A4 c.919-2A>G, and MT-RNR1 m.1555A>G." (PMID 36568381, 2022).
hearing loss (continued). "In the clinic, GJB2 mutations cause various auditory phenotypes, including profound sensorineural hearing loss or late-onset progressive hearing loss." (PMID 35688810, 2022). "Because of the great diversity of autosomal recessive NSHL, epidemiological investigations across a diverse range of ethnic groups are required to determine the prevalence of GJB2 mutations as a cause of hearing impairment." (PMID 35707775, 2022). "Gap junction protein beta 2 (GJB2) (connexin 26) variants are commonly implicated in non-syndromic hearing impairment (NSHI)." (PMID 35336849, 2022). "The total contribution of the genes studied in this work to non-GJB2-related hearing loss was 21% (48/226)." (PMID 36555390, 2022). "Our findings provide evidence for the immune response as promising new therapeutic targets for the prevention of Gjb2-related hearing loss." (PMID 35688810, 2022). "With regard to the causative gene of mild-to-moderate hearing loss the GJB2 gene has been known to have genotype/phenotype correlations, and p.V37I variant-associated hearing loss is mild-to-moderate." (PMID 34599366, 2022). "The most common disease carried by individuals was GJB2 (OMIM: 121,011), with a 20.17% carrier frequency, which is associated with GJB2-related hearing loss." (PMID 36072675, 2022). "Pathogenic variants in genes involved in SHL accounted for almost half of the cases with an established molecular genetic diagnosis, which were 10% of the total cohort of patients with non-GJB2-related hearing loss." (PMID 36555390, 2022). "The prevalence of hereditary hearing impairment due to mutations in the GJB2 gene is 1 per 1000 newborns." (PMID 36579563, 2022). "Rare mutations that contribute to about half of congenital non‐syndromic hearing impairment in European populations are clustered in the GJB2 gene, but these mutations have limited predictive relevance in sub‐Saharan African populations." (PMID 35842778, 2022). "We also excluded the patients without hearing thresholds information and two severe-to-profound hearing loss patients carrying both of GJB2 and STRC biallelic mutations." (PMID 35022556, 2022). "A confirmed or presumed genetic cause of hearing loss was found for 50% of patients (n = 17), including 12 patients with a confirmed mutation of GJB2 (CONNEXINE 26 gene)." (PMID 35407482, 2022). "Because of a high GJB2 carrier frequency, follow-up for non-syndromic hearing loss will be required in one-fourth of Southern Chinese individuals." (PMID 35314707, 2022). "GJB2 germline mutations have been previously reported in congenital hearing loss and rarely been reported in cancer." (PMID 36451132, 2022). "The contribution of the genes studied in this work to non-GJB2-related hearing loss was 21% (48/226)." (PMID 36555390, 2022). "Of the 52 patients with hearing loss, genetic factors were identified for 39 patients (75.0%); GJB2 and SLC26A4 were the most common genes identified." (PMID 35816303, 2022). "The diagnostic yield is lower in patients who test positive for mutations in the GJB2 gene, which is the most common cause of nonsyndromic hearing loss." (PMID 36529647, 2022). "To date, in Russia, there have been relatively few studies that apply massive parallel sequencing (MPS) methods to elucidate the genetic factors underlying non-GJB2-related hearing loss cases." (PMID 36555390, 2022). "It is the second most common etiology in cases of mild-to-moderate hearing loss, after the GJB2 gene." (PMID 35571039, 2022). "Several mutations affecting the GJB2 gene are known to give rise to hearing loss of varying severities, and there is an active search for therapeutic options." (PMID 36204137, 2022). "Conversely, another study noted a much smaller rate of PVL, 23% (3/13), in a similar group of children with GJB2 mutations causing hearing loss." (PMID 34744965, 2021).
hearing loss (continued). "In a large cohort of patients with hearing loss, 3.89% of the patients were patients with a heterozygous pathogenic GJB2 variant yet, in the general population, the frequency was lower at 2.45%." (PMID 34062854, 2021). "If we subtract these clarified patients (29.5%) from the detected frequency (3.89%), we find that the frequency of individuals with a heterozygous pathogenic GJB2 variant with hearing loss versus the general population is almost the same (3.89–1.15%)." (PMID 34062854, 2021). "The panel of transgenic human cell lines with a stable expression of different GJB2 variants (wild type and mutants associated with hearing loss) was generated for in vitro analysis of functional effect of c.516G>C (p.Trp172Cys)." (PMID 33466560, 2021). "In our study, we aimed to detect the cause of hearing loss in patients with only one pathogenic GJB2 variant." (PMID 34062854, 2021). "Mutations in Gja1 (Cx43), Gjb2 (Cx26), Gjb3 (Cx31), and Gjb6 (Cx30), which constitute gap junctions, can cause non-syndromic hearing loss." (PMID 34199197, 2021). "Screening of 35delG was performed using ARMS‐PCR, and eight of the families were observed with 35delG in the homozygous form, accounting for about 61.5% of GJB2‐related hearing loss in the study." (PMID 34581455, 2021). "One study showed 66% (11/24) of children with non-syndromic hearing loss due to mutations in GJB2 were noted to have PVL." (PMID 34744965, 2021). "Mutations in GJB2 are the most common cause of moderate-to-profound congenital inherited hearing impairment in numerous populations." (PMID 35126756, 2021). "Among these hearing loss genes, GJB2 and SLC26A4 gene variants were most common in Chinese deaf population." (PMID 34335733, 2021). "For comparative in vitro analysis of the functional effect of c.516G>C (p.Trp172Cys), we generated the panel of transgenic human cell lines with a stable expression of different GJB2 variants (wild type and mutants associated with hearing loss)." (PMID 33466560, 2021). "Published studies of peripheral vestibular loss in the setting of non-syndromic genetic hearing loss particularly sparse, although there has been a limited number of investigations of vestibular function in patients with mutations in the GJB2 gene." (PMID 34744965, 2021). "The GJB2 gene encoding the gap-junction protein Connexin 26 caused different forms of hearing impairment, in particular autosomal recessive non-syndromic hearing impairment." (PMID 35126756, 2021). "In this study, we focused on some unconditional cases involving GJB2 c.235delC homozygotes, whose phenotypes were late-onset and/or moderate hearing loss." (PMID 33718389, 2021). "Cellular and deafness mechanisms underlying GJB2 induced hearing impairment are currently unclear, although numerous clinical reports indicate that Connexin26 mutations are associated with hearing impairment." (PMID 33718389, 2021). "Last year, we published a study where 21% of 197 Czech patients with hearing loss, and where GJB2 pathogenic variants had already been excluded, were clarified by a NGS gene panel." (PMID 34062854, 2021). "In the Czech Republic, among patients with hearing loss, the c.35delG variant accounts for 82.8% of all pathogenic GJB2 variants." (PMID 34062854, 2021). "A possible reason for an excess of the GJB2 heterozygotes among hearing loss patients is the small/limited number of patients included in the previous studies, at least among Czech patients." (PMID 34062854, 2021). "In conclusion, we presented some functional evidences supporting the pathogenicity of the rare missense variant c.516G>C (p.Trp172Cys) in the GJB2 gene associated with nonsyndromic recessive hearing loss (DFNB1)." (PMID 33466560, 2021). "We previously showed that disruption of CX26-GJPs is associated with Gjb2-related hearing-loss pathogenesis and that assembly of cochlear GJPs is dependent on CX26." (PMID 33968919, 2021).
hearing loss (continued). "one case with homozygous variant c.[235del] in GJB2 was referred bilaterally for hearing screening and developed moderate hearing loss, but her linguistic competence was normal." (PMID 34276761, 2021). "It is found that genetic alterations in GJB2 are also the most primary cause of nonsyndromic hearing loss in South Asia." (PMID 34695157, 2021). "Mutations in the GJB2 gene encoding transmembrane protein connexin 26 (Cx26) are the most common cause for hearing loss worldwide." (PMID 33466560, 2021). "Since GJB2 is the primary connexin gene linked to sensorineural hearing loss and its mechanism of action in the cochlea remains uncertain, it is the connexin of focus in the present study." (PMID 32300592, 2020). "Currently, it is estimated that there are more than 100 causative genes related to non-syndromic hereditary hearing loss, with the most frequent deafness-associated gene worldwide being the GJB2 gene." (PMID 32120898, 2020). "To elucidate the molecular etiology of the hearing loss in probands with mono-allelic GJB2 mutations, we further sequenced 139 known deafness-related genes by targeted NGS in 44 such probands with good quality and quantity of DNA samples." (PMID 31992338, 2020). "For instance, the SNP rs72474224 C > T in GJB2 is commonly liked to non-syndromic hearing loss and deafness, which is also the most prevalent genetic disorder in the Vietnamese population." (PMID 33154511, 2020). "Another result determined in the present study was the presence of c.-23+1G>A, rs80338940 formerly called IVS1+1G>A, which is a splice site mutation found in exon 1 and intron 1 of GJB2 gene in patients with hearing impairment." (PMID 33333757, 2020). "In Ghana, gap-junction protein β 2 (GJB2) variants account for about 25.9% of familial hearing impairment (HI) cases." (PMID 32012697, 2020). "In the current study we move one step closer to understanding how various GJB2 gene mutations cause hearing loss by exploring their characteristics in cochlear-relevant cells obtained from the developing organ of Corti." (PMID 32300592, 2020). "In this study, we presented an overview on the mutation spectrum of GJB2 in a large cohort (n = 1852) of patients with hearing loss in Chinese Hans." (PMID 31992338, 2020). "Hearing loss caused by GJB2 gene mutations is divided into autosomal recessive inheritance (DFNB1A) and autosomal dominant inheritance (DFNA3A), but most cases of GJB2-associated hearing loss are autosomal recessive inheritance." (PMID 32120898, 2020). "GJB2 is the most prevalent gene known to be responsible for congenital hearing loss worldwide, and consequently is the focus of universal newborn hearing screening programs." (PMID 32027099, 2020). "Pathogenic mutation of GJB2, which encodes the gap junction protein connexin 26 (Cx26), is the most common cause of hearing loss in many populations." (PMID 32090102, 2020). "A study of the association between hearing loss and ER stress showed that, in cells carrying mutated GJB2, the corresponding mutant protein accumulated in the ER and failed to move to the plasma membrane, causing hearing loss." (PMID 33147893, 2020). "In the past, many non-tissue relevant and often cancerous cell lines have been used to express Cx26 mutants to uncover that GJB2 gene mutations linked to hearing loss fall into either loss-of-function or gain-of-function mutations." (PMID 32300592, 2020). "The drive for an efficient and cost-effective test was from the fact that the founder mutation, GJB2-p.Arg143Trp, is the most common variant associated with hearing impairment in Ghana." (PMID 32012697, 2020). "On the other hand, a majority of GJB2 mutations are inherited in a recessive form and lead to non-syndromic hearing loss DFNB1." (PMID 31992338, 2020). "The genetic panel report for hearing loss has detected a mutation in the GJB2 gene, ruling out the possibility of association with intrauterine exposure to the Zika virus." (PMID 33233769, 2020).